IL4 (interleukin 4)
Diseases named in the same sentence as IL4 in open-access papers (continued):
Sharing a sentence is not in itself a finding about the gene and the disease.
chronic myeloid leukemia (3 papers, 2021 to 2024). "TGF-ß-mediated signals were found to be activated in mouse chronic myeloid leukemia-initiating cells in vitro and elevated transcript levels of IL-4 were found in human primary chronic myeloid leukemia cells." (PMID 38500877, 2024). "This has been studied in the context of chronic myeloid leukemia, a condition where iNKT activity, a major source for IL-4 production, is reduced." (PMID 34398252, 2021). "The first indication for IL-4 being important for human TAIM differentiation is that the percentage of TAIM-phenotype cells is decreased in chronic myeloid leukemia, and that this decrease can be partially restored after complete remission of chronic myeloid leukemia." (PMID 34398252, 2021).
coagulation disorders (3 papers, 2020 to 2022). "Most biomarkers are related to the immune system (SAA,TNF-∝, and IP-10) or coagulopathies (D-dimer, antithrombin, and VWF) and a few have already been established as cancer biomarkers (ACE2, IL-6, IL-4 and IL-2)." (PMID 32935101, 2020).
Coeliac disease (3 papers, 2015 to 2023). "When further studies will confirm the relevance of TCRγδ+ and IL4+ T cells as specific biomarkers of CD lesion evolution, their detection can be applied in clinical practice to assess the efficacy of new drugs for celiac disease treatment alternative to a gluten-free diet." (PMID 34834386, 2021). "Conversely, the related Th2 cytokine IL-4 was low in coeliac disease compared to controls (although not significantly), similar to other studies 4,5, reflecting the inverse relationship between IFN-γ and IL-4 production." (PMID 25212572, 2015).
Constipation (3 papers, 2023 to 2025). Infrequent or difficult evacuation of feces. "The increased mRNA levels of four cytokines, including tumor necrosis factor-α (TNF-α), interleukin (IL)-6, IL-4, and IL-1β, were remarkably recovered in Lop-induced constipation rats after treatment with MPC." (PMID 39857371, 2024).
delirium (3 papers, 2022 to 2025). A disorder characterized by confusion; inattentiveness; disorientation; illusions; hallucinations; agitation; and in some instances autonomic nervous system overactivity. "The second major finding of this study is that the CIRS index and IL-4 and sIL-RA, which display anti-inflammatory effects, are inversely associated with delirium and/or the severity of delirium symptoms." (PMID 35641947, 2022). "The first major finding of this study is that delirium and/or the severity of delirium symptoms are significantly associated with the IRS/CIRS ratio, namely positively with M1 (i.e. IL-6, CXCL8 and TNF-α), Th1 and Th17 activation and T cell growth (positively), and inversely with IL-4 and sIL-1RA." (PMID 35641947, 2022).
dental caries (3 papers, 2021 to 2025). The decay of a tooth, in which it becomes softened, discolored, and/or porous. "Among the six interleukins measured, only IL-4 and IL-15 showed a significantly higher level in the group of children with dentofacial tissue inflammation compared to the group with uncomplicated dental caries." (PMID 39201367, 2024). "The current research identified four biomarkers (IL-4, IL-13, IL-2-RA, and eotaxin/CCL11) that enabled the correct diagnosis of dental caries in 37 out of 38 patients using RF analysis." (PMID 33806927, 2021). "We suggest a further validation of the four biomarkers (IL-4, IL-13, IL-2-RA, and eotaxin/CCL11) in the context of JAK/STAT signaling and dental caries." (PMID 33806927, 2021).
diffuse large B-cell lymphoma (3 papers, 2020 to 2021). "Loss of Mll4 causes a proliferative advantage that expands the germinal centre (GC), which is enhanced by CD40 and IL4 stimulation and represents the cell type that is causative to diffuse large B-cell lymphomas (DLBCL) and follicular lymphomas (FL)." (PMID 32389825, 2020). "IL-4 increased the sensitivity of diffuse large B-cell lymphoma (DLBCL) subtype to doxorubicin-induced apoptosis and complement-dependent rituximab cell death." (PMID 33321722, 2020).
endometrial cancer (3 papers, 2019 to 2024). Primary or metastatic malignant neoplasm involving the endometrium (mucous membrane that lines the endometrial cavity). "Given the scarcity of data on these proteins in endometrial cancer, this study aims to evaluate the diagnostic potential of preoperative serum concentrations of IL-4, IL-7, IL-9, IL-10, NT, TSP-2, and NRP1." (PMID 39334861, 2024). "Although in recent years there has been growing interest in the potential use of Interleukin-4 as a marker in the serum of patients with various types of cancers, its role in endometrial cancer remains controversial." (PMID 39334861, 2024). "All these studies indicate an undeniable role in the pathogenesis of tumor development, but despite promising results, further research is necessary to confirm the role of IL-4 as a marker in endometrial cancer." (PMID 39334861, 2024). "Combining IL-4, IL-8, CA125, and menopausal status improved the accuracy of assessing endometrial cancer risk." (PMID 38464838, 2024). "In conclusion, this study is novel in demonstrating the association between IL4, IL6 gene polymorphisms and susceptibility to endometrial cancer in Chinese Han women." (PMID 30828987, 2019). "In endometrial cancer, IL-4’s role as a potential biomarker remains to be fully understood." (PMID 39334861, 2024). "Our study aimed to determine whether IL-4, IL-7, IL-9, IL-10, NT, TSP-2, and NRP1 could be diagnostic markers for endometrial cancer in women." (PMID 39334861, 2024). "This study sought to investigate whether the IL4, IL6 two gene genetic variants were associated with susceptibility to endometrial cancer (EC) in Hainan Chinese Han women by a hospital‐based study." (PMID 30828987, 2019). "IL-4, IL-7, IL-9, NT, and NRP1 may be useful diagnostic markers for endometrial cancer." (PMID 39334861, 2024). "This study suggests the clinical utility of IL-4, IL-7, IL-9, NT, and NRP1 in the diagnosis of endometrial cancer." (PMID 39334861, 2024). "The initial study presented here demonstrates the clinical utility of IL-4, IL-7, IL-9, NT, and NRP1 in endometrial cancer." (PMID 39334861, 2024). "Finally, we evaluated the significance of IL-4, IL-7, IL-9, IL-10, NT, TSP-2, and NRP1 in the diagnosis of endometrial cancer." (PMID 39334861, 2024). "In conclusion, the rs1524107 (T/C) and the rs2066992 (T/G) in IL6 gene seem to be relevant to increased susceptibility to endometrial cancer, which suggests IL6 may play a role in EC, however, in IL4 gene, we did not found any SNPs were imposed significant with EC risk." (PMID 30828987, 2019). "The purpose of this study was to determine if IL-4, IL-7, IL-9, IL-10, NT, TSP-2, and NRP1 could be used as novel, helpful markers for the detection of endometrial cancer." (PMID 39334861, 2024).
enteropathy (3 papers, 2014 to 2017). "Interleukin (IL)-4 production by CD4+ T cells was measured as a causative factor of enteropathy, and anti-IL-4 antibody was used to reveal the role of Foxp3+ OVA-specific Tregs (aiTreg) in this process." (PMID 28234975, 2017). "Excessive IL-4 levels in the MLNs directly inhibited the induction of aiTregs and caused enteropathy." (PMID 28234975, 2017). "In the MLNs of EW-fed OVA23-3 or R23-3 mice, excessive and persistent production of IL-4 attenuated the percentage of Tregs and caused enteropathy on days 7–10." (PMID 28234975, 2017). "Continued feeding of the EW diet until day 28 enabled the OVA23-3 and R23-3 mice to recover from the enteropathy, with a decrease in the excessive IL-4 production by OVA-specific CD4+ T cells and with an increase in the percentage of aiTregs." (PMID 28234975, 2017). "Injecting mice with anti-IL-4 antibody or cyclosporine A confirmed the involvement of Th2 cells in the development of the enteropathy." (PMID 25290461, 2014). "Furthermore, the increased enteropathy, the reduced inflammatory cytokine levels, the altered IL-4 and IL-13 levels, and increased IgE levels suggest that serglycin proteoglycans have a regulatory role in the immune response during T. spiralis infection." (PMID 27267469, 2016). "Although aiTregs suppress the proliferation of T cells, they may not easily inhibit the IL-4 production of OVA-specific CD4+ T cells, and aiTregs might be reprogrammed to Th2 cells themselves in a T-cell-dependent manner and aggravate enteropathy." (PMID 28234975, 2017).
enthesitis (3 papers, 2021 to 2024). Inflammation at the site of insertion of ligaments, tendons, and other fibrous structures into bone. "The mechanism surrounding IL-4/IL-13 blocking-induced enthesitis are presently unknown, but genetic associations of unknown functional significance between IL-13 and psoriatic arthritis have been reported." (PMID 33544244, 2021). "The relationship between IL-4 and AS has not been reported, but IL-4 plays an important role in in inflammatory arthritis and enthesitis." (PMID 38054001, 2023).
eosinophilic gastroenteritis (3 papers, 2019 to 2025). "In particular, disruption of the PD-1–PD-L1 axis has been implicated in eosinophilic pneumonia via Th2 cytokines such as IL-4, -5, and -13, while eosinophilic enteritis indicates similar gut mucosal activation." (PMID 40723182, 2025). "Transcriptomic analysis of gastric biopsies obtained from patients with eosinophilic gastroenteritis reveals activation of the Th2 cytokine signaling pathways IL-4, IL-5, and IL-13." (PMID 31730503, 2019).
exanthema (3 papers, 2014 to 2023). "Some positive clinical correlations (weak to moderate) of interest need to be mentioned- IFN-γ and pain intensity, IFN-β, IL-1β individually and fatigue, TNF-α and headache, IL-4 and myalgia, IL-6 and skin rash." (PMID 25343623, 2014). "Interestingly, exanthema was strongly associated with IFN-γ (p = 0.0017), IL-4 (p = 0.0018), IL-5 (p = 0.0047), and CXCL10 (p = 0.0029)." (PMID 37235332, 2023).
falciparum malaria (3 papers, 2012 to 2018). "However, our findings show that the high IL-4 producing haplotype TTR2 protects or increases survival against Plasmodium falciparum malaria." (PMID 23110190, 2012). "Compared to control children (n = 106), children with moderately severe (n = 77) and severe falciparum malaria (n = 129) had significantly higher mononuclear cell arginase 1 mRNA, protein, and enzyme activity; lower NOS2 mRNA; lower plasma arginine; and higher plasma IL-10, IL-13, and IL-4." (PMID 27385484, 2016).
Fibroadenoma (3 papers, 2022 to 2025). A benign tumor of the breast characterized by the presence of stromal and epithelial elements. "In patients with BC and fibroadenomas, the levels of IL-1β (p = 0.0123), IL-4 (p = 0.0001), and IL-10 (p = 0.0000) were significantly higher than the norm and statistically significantly different from the control values." (PMID 40429927, 2025).
gestational diabetes (3 papers, 2018 to 2025). Carbohydrate intolerance first diagnosed during pregnancy. "A previous study suggested that pEVs from patients with gestational diabetes mellitus (GDM) activate endothelial cells, leading to high level of cytokine secretion, including IL-4, IL-6, IL-8, IFN-γ, TNF-α." (PMID 39996028, 2025).
hay fever (3 papers, 2006 to 2024). "Total IgE levels were elevated among participants with hay fever exhibiting IL4(-589C>T) TT genotype (p = 0.02)." (PMID 16759385, 2006).
Headache (3 papers, 2022 to 2025). Cephalgia, or pain sensed in various parts of the head, not confined to the area of distribution of any nerve. "Omega-3 fatty acids (which have known anti-inflammatory effects by generating resolvins) consistently improved headache outcomes and raised IL-4/lowered IFN-γ 9, as well as reduced IL-6 in combination with curcumin." (PMID 41377228, 2025). "Another anti-inflammatory cytokine IL-4 was found higher during the follow-up in people with headaches." (PMID 36561720, 2022).
herpes zoster (3 papers, 2016 to 2025). A common dermal and neurologic disorder caused by reactivation of the varicella-zoster virus that has remained dormant within dorsal root ganglia, often for decades, after the patient's initial exposure to the virus in the form of varicella (chickenpox). "In patients with herpes zoster, the serum level of IL-17, IL-23, IL-21, IL-4 and IL-12 as well as VZV IgG antibodies titer were statistically significantly increased compared to control group." (PMID 26934574, 2016). "The fluid in skin blisters and peripheral blood of herpes zoster patients has low levels of the Th1 cytokines interleukin (IL)-2 and tumor necrosis factor-α and high levels of the Th2 cytokines IL-10 and IL-4 compared with the levels of these cytokines in samples from a control group." (PMID 32944021, 2020). "In the present study we investigated the serum cytokine profile (IL-17, IL-23, IL-21, IL-4, IL-12), representing cellular and humoral immunity and assessed the level of VZV IgG antibodies in patients with herpes zoster." (PMID 26934574, 2016). "We investigated the serum concentrations of IL-17, IL-23, IL-21, IL-4, IL-12 and the level of VZV IgG antibodies in 23 patients with herpes zoster who did not develop superinfection." (PMID 26934574, 2016).
hip fracture (3 papers, 2013 to 2022). Traumatic or pathological injury to the hip in which the continuity of either the femoral head, femoral neck, intertrochanteric or subtrochanteric regions is broken. "Unsurprisingly, our study also observed significantly increased levels the Th1 (combination of IL-2, IFN-γ and IL-12) and T cell growth and activation factors (a combination of IL-4, IL-7, IL-9, IL-12, IL-15, GM-CSF) in the delirious hip fracture patients compared to the non-delirious group." (PMID 35641947, 2022).
Hodgkins lymphoma (3 papers, 2013 to 2025). A heterogeneous group of malignant lymphoid neoplasms of B-cell origin characterized histologically by the presence of Hodgkin and Reed-Sternberg (HRS) cells in the vast majority of cases. "In Hodgkin lymphoma and cutaneous T cell lymphoma (CTCL), CCL26 recruits CCR3+ T lymphocytes into TIME, where they secrete high levels of IL-4—a hallmark of a T helper 2 (Th2)-dominant microenvironment that is closely associated with CTCL development." (PMID 41280721, 2025). "We therefore propose that the regulation by EBV of genes at the intersection of IFN and IL-4 pathways that occurs early following infection of B cells has relevance to the development or maintenance of an EBV-associated malignancy, Hodgkin's lymphoma." (PMID 23724103, 2013).
Huntington disease (3 papers, 2022 to 2026). Huntington disease (HD) is a rare neurodegenerative disorder of the central nervous system characterized by unwanted choreatic movements, behavioral and psychiatric disturbances and dementia. "A previous study showed that a higher relative abundance of Intestinimonas genera is associated with elevated levels of IL-4, suggesting that alterations in the composition of the gut microbiota may play a role in contributing to systemic inflammation in patients with Huntington’s disease." (PMID 38999941, 2024). "For example, an increase in the abundance of g_Intestinimonas was observed in Huntington's disease, and it was positively correlated with IL-4 levels in the blood, demonstrating anti-inflammatory activity." (PMID 35958910, 2022).
hyperthyroidism (3 papers, 2005 to 2025). Overactivity of the thyroid gland resulting in overproduction of thyroid hormone and increased metabolic rate. "It was reported that NF-κB is activated by hyperthyroidism, which is crucial for controlling the genetic transcription and encoding of inflammatory cytokines including IL-10, IL-4, TNF-α, and IL-6 that, in turn, promote NO, lipid peroxidation and free radical generation." (PMID 37020549, 2023). "The level of the pro-inflammatory markers (TNF-α, IL-1, IL-4, IL-6, and IL-10) in the hyperthyroidism group of rats was much higher than that of the healthy animals, whereas the level of the apoptotic marker (CD4+) was noticeably lower." (PMID 37020549, 2023). "Once infected with H. pylori, cytokines such as interleukin (IL)-4, IL-5, and IL-6 are activated, initiating a cascade of humoral immune responses that may modify the expression of adhesion molecules on the gastric mucosa, thereby contributing to the hyperthyroidism observed in GD." (PMID 39963276, 2025). "Interestingly, treatment of hyperthyroidism-modeled group with hesperidin therapy dramatically decreased blood levels of TNF-α, IL-1, IL-4, IL-6, and IL-10 while sharply increasing CD4+ level close to healthy controls." (PMID 37020549, 2023). "The findings showed that hesperidin significantly modulated hyperthyroidism deteriorations, this was evidenced by a remarkable decline in serum T4, FT4, T3, FT3, TNF-α, IL1β-, IL4-, IL-6, and IL-10 levels, with a minor increase in TSH and significant raise in CD4+ level." (PMID 37020549, 2023). "IL-4 mediates TH2 type mechanism, which can lead to hyperthyroidism." (PMID 15762980, 2005).
ichthyosis (3 papers, 2022 to 2025). Disorders of cornification that are characterized by visible scaling and/or hyperkeratosis of most or all of the skin. "g., anti-TNF-α, anti-IL-17, and anti-IL-4/IL-13 antibodies) have been reported as useful treatments for several types of inherited ichthyoses." (PMID 36332686, 2022).
imbalance (3 papers, 2022 to 2025). "Representative cytokines for these pathways, IL-4 or IFN-γ, can serve as indicators of immune imbalance." (PMID 41309385, 2025).
irritable bowel syndrome (3 papers, 2016 to 2025). Irritable bowel syndrome (IBS) is a chronic functional condition of the lower gastrointestinal (GI) tract characterized by abdominal pain or discomfort and disordered bowel habit (diarrhea, constipation, or fluctuation between the two). "There were reports showed that IL-4 was up-regulated in acute stage of mice with postinfectious irritable bowel syndrome, but restored to normal and even reduced." (PMID 27896022, 2016).
kidney (3 papers, 2018 to 2023). "IL-4-secreting Th cells were found to be protective in kidney transplant recipients." (PMID 34017323, 2021). "We compared markers of kidney inflammation and injury (neutrophil gelatinase-associated lipocalin, kidney injury molecule-1) as well as plasma and urine levels of T cell-associated cytokines (TNF-α, interferon-γ, interleukin (IL)-2, IL-4, IL-6, IL-8, IL-9, and IL-10) between groups." (PMID 36938084, 2023).
lichen sclerosus (3 papers, 2016 to 2024). "The response of vulvar lichen sclerosus to dupilumab may indicate that the IL-4/IL-13 signaling pathway plays a role in the pathogenesis of lichen sclerosus." (PMID 38988357, 2024). "Although previous studies have shown the presence of Th1 activity in the labia lichen sclerosus, further research is needed to elucidate the potential role of Th2 and IL-4/IL-13 cytokines in vulvar and nonvulvar lichen sclerosus." (PMID 38988357, 2024).
macrophage activation syndrome (3 papers, 2014 to 2021). A complication of rheumatic disease that is caused by excessive activation and uncontrolled proliferation of T lymphocytes and well-differentiated macrophages. "This suggested an exacerbated response in RELMα deficiency, similar to the macrophage activation syndrome caused by sustained IL-4 exposure." (PMID 34349768, 2021).
male infertility (3 papers, 2022 to 2025). The inability of the male to effect fertilization of an ovum after a specified period of unprotected intercourse. "The imbalance of some cytokines such as IL-4 can cause male infertility." (PMID 35739948, 2022).
mantle cell lymphoma (3 papers, 2016 to 2021). Mantle cell lymphoma is a rare form of malignant non-Hodgkin lymphoma affecting B lymphocytes in the lymph nodes in a region called the ``mantle zone''. "We found that IL-4 induces the expression of DOCK10 in lymphoid neoplasms such as mantle cell lymphoma and DLBCL, and we confirmed that IL-4 induces cytoplasmic levels of DOCK10 in CLL." (PMID 34449554, 2021).